ALB (albumin)
Diseases named in the same sentence as ALB in open-access papers (continued):
Sharing a sentence is not in itself a finding about the gene and the disease.
appendicitis (10 papers, 2020 to 2026). Acute inflammation of the vermiform appendix. "In addition, ratios derived from CBC parameters (such as the systemic immune inflammatory index) and other biomarkers such as ischemia-modified albumin have been reported as potential diagnostic tools, particularly in pediatric appendicitis, where diagnosis can be challenging." (PMID 37894416, 2023). "Eligible studies included participants aged 0-18 years and reported BMI-based measures and/or biochemical nutritional markers (e.g., albumin, prealbumin, or derived inflammation-nutrition indices) stratified by perforation or complicated appendicitis." (PMID 41897039, 2026). "These two variables—lymphocyte count and CRP/albumin ratio—resulted particularly abnormal in patients with gangrenous appendicitis." (PMID 36707812, 2023). "Albumin, CRP, lymphocytes count, neutrophils count, WBC count, CRP/Albumin ratio, CRP/MPV ratio, albumin/MPV ratio and neutrophils/lymphocytes ratio were found to be directly or inversely associated with severity of appendicitis." (PMID 36707812, 2023). "In fact, our simplified predictive model considers only low lymphocyte count and high CRP to albumin ratio to significantly correlate with the presence of gangrenous appendicitis." (PMID 36707812, 2023). "Moreover, the role of ischemia-modified albumin has been reported to assist in diagnosing pediatric appendicitis." (PMID 37894416, 2023). "In other words, low lymphocyte count and CRP/Albumin can be used as markers to select those patients with acute right iliac fossa pain who would benefit from an operation of appendicectomy, i.e. those with gangrenous appendicitis, among those who have a clinical diagnosis of acute appendicitis." (PMID 36707812, 2023). "Similarly, while CRP per se did not qualify as a diagnostic tool in our study, the CRP to Albumin ratio is significantly and independently associated with severity of appendicitis." (PMID 36707812, 2023). "One such marker is serum ischemia-modified albumin (IMA), which can be a novel biomarker for accurately diagnosing and prognosticating acute appendicitis." (PMID 37685553, 2023). "In children below 4 years of age, the perforated appendicitis group exhibits lower levels of hemoglobin, albumin, and prealbumin compared to the non-perforated appendicitis group (p < 0.05)." (PMID 38509094, 2024). "The purpose of this research is to determine if the hemoglobin, albumin, lymphocyte, and platelet (HALP) and modified HALP (m-HALP) scores differ between complicated and uncomplicated appendicitis in patients diagnosed with AA who have applied to the emergency department (ED)." (PMID 39070943, 2024). "Low lymphocyte count and high CRP/Albumin ratio combined into a predictive model may have a role in the selection of patients who deserve appendicectomy instead of non-operative management of acute appendicitis." (PMID 36707812, 2023). "During the acute inflammatory phase of appendicitis, the positive acute-phase protein CRP increases, while the negative acute-phase protein albumin decreases." (PMID 41141923, 2025). "Furthermore, significant variations existed between the perforated and non-perforated appendicitis groups in terms of WBC counts, neutrophils ratio, lymphocytes ratio, CRP, procalcitonin, total bilirubin, direct bilirubin, albumin, prealbumin, and other laboratory test results (p < 0.05)." (PMID 38509094, 2024).
bipolar disorder (10 papers, 2012 to 2025). A disorder of the brain that causes unusual shifts in mood, energy, activity levels and the ability to carry out day-to-day tasks. "The CSF/serum albumin ratio was numerically somewhat higher in the bipolar disorder group, with mean ± SD values of 5.7 ± 2.6 for type 1 and 5.3 ± 2.8 for type 2, compared to 4.5 ± 1.6 in healthy controls." (PMID 40717781, 2025). "In bipolar depression, the intricate relationship of zinc, albumin, IL-6, and CRP with the symptoms assessed using the HAMD-17 and MADRS scales reveals a more complex interaction." (PMID 38785543, 2024). "However, in the bivariate regression adjusted for antidepressant use, albumin levels were a significant predictor in the bipolar depression group, reducing the likelihood of a severe depressive episode (OR = 0.86)." (PMID 38785543, 2024). "Interestingly, in patients with bipolar depression, severe depressive episode (evaluated according to Hamilton Scale), albumin values were significantly lower compared to the moderately severe depressive episode of the same participants group (Mann–Whitney U test, p = 0.042)." (PMID 38785543, 2024). "Some examples of biochemical traits correlated with two or fewer psychiatric GWAS were albumin and ADHD (rg = −0.151), mean corpuscular volume and AN (rg = 0.087), mean sphered cell volume and SZ (rg = 0.06), and creatinine with bipolar disorder (BIP) and SZ (SZ: rg = −0.07; BIP: rg = −0.106)." (PMID 35385317, 2022).
bleeding disorder (10 papers, 2020 to 2025). "However, albumin solutions do not contain important plasma components including coagulation factors and immunoglobulins; TPE using an albumin solution would not replenish these components, which makes it difficult to recommend albumin solutions in cases with hemorrhagic disease and infection." (PMID 38672203, 2024).
clear cell renal cell carcinoma (10 papers, 2017 to 2025). "Chang first used SIS in predicting the prognosis of patients with renal clear cell carcinoma, which was based on preoperative serum ALB and median LMR." (PMID 37388223, 2023). "In this retrospective analysis, we evaluated associations between albumin to globulin ratio (AGR), clinicopathological characteristics, and survival in 592 patients with localized or locally advanced clear cell renal cell carcinoma (CCRCC) prior to nephrectomy." (PMID 28187463, 2017).
erectile dysfunction (10 papers, 2007 to 2026). Persistent or recurrent inability to achieve or to maintain an erection during sexual activity. "In this nationally representative NHANES 2001–2004 study, we demonstrated an inverse relationship between serum albumin levels and erectile dysfunction (ED) risk after controlling for confounders." (PMID 39913554, 2025). "First, given the cross-sectional nature of this study, we cannot establish causality between albumin levels and erectile dysfunction (ED)." (PMID 39913554, 2025). "stratified analysis and interaction tests of serum albumin levels and erectile dysfunction risk in U.S. adults: NHANES 2001–2004." (PMID 39913554, 2025). "Our findings corroborate and extend previous clinical evidence indicating an inverse correlation between serum albumin levels and the risk of erectile dysfunction (ED)." (PMID 39913554, 2025). "Association between serum albumin levels and erectile dysfunction across different regression models." (PMID 39913554, 2025). "Higher plasma albumin levels may reduce the risk of erectile dysfunction in men through multiple pathways." (PMID 39913554, 2025). "The demonstrated inverse relationship between serum albumin and erectile dysfunction suggests that albumin assessment, a routine laboratory measurement, should be considered in ED evaluation." (PMID 39913554, 2025). "The aim of this study is to investigate the association between Serum Albumin Levels (ALB) and erectile dysfunction (ED) within the U.S. general population." (PMID 39913554, 2025). "This study explored the association between the C-reactive protein-albumin-lymphocyte (CALLY) index and erectile dysfunction (ED)." (PMID 40099259, 2025). "The blinded control group, which was treated with albumin only, demonstrated a significant reduction for increased ICP of 40.0 ± 6.3 cmH2O, consistent with a state of erectile dysfunction." (PMID 17341313, 2007). "Epworth sleepiness scale, apnoea‐hypopnea index score, O2 saturation‐nadir, oxygen desaturation index and albumin were higher compared to patients without erectile dysfunction." (PMID 35817418, 2022). "The relationship between hormonal and biochemical parameters in the men showed that those with erectile dysfunction had statistically significantly lower TT concentration (p = 0.018), SHBG concentration (p = 0.026), and albumin concentration (p = 0.029) than those without dysfunction." (PMID 35805249, 2022).
Guillain-Barre syndrome (10 papers, 2014 to 2026). A spectrum of rare post-infectious neuropathies that usually occur in otherwise healthy patients. "Low albumin in neurological diseases is associated with poor prognosis in Guillain-Barre syndrome (GBS) treated with IVIg15." (PMID 29343812, 2018). "Initial investigations revealed albumin-cytologic dissociation in the cerebrospinal fluid, raising suspicion of Guillain-Barré syndrome, for which intravenous immunoglobulin was administered; however, there was no clinical improvement." (PMID 41669610, 2026). "The cerebrospinal fluid analysis revealed inflammatory fluid with pleocytosis and cytological albumin dissociation in patients with Guillain-Barré syndrome." (PMID 37509537, 2023). "PE can also be conducted with albumin and gelatin, instead of fresh frozen plasma (French Cooperative Group on Plasma Exchange in Guillain-Barre syndrome, 1987)." (PMID 33995011, 2021). "Serum albumin has been suggested as a prognostic factor in various diseases, including Guillain-Barre syndrome (GBS)." (PMID 31231392, 2019). "CSF analysis showed normal albumin and protein; however, with the features of paraplegia with flaccidity, areflexia, absence of bowel and bladder symptoms, and MRI ruling out other possibilities, a diagnosis of Guillain-Barre syndrome (GBS) was made." (PMID 37139032, 2023). "Bilateral facial diplegia without weakness and paresthesia is a variant of Guillain-Barre syndrome that mostly presents with acute onset, rapid progression with or without limb weakness, paresthesia, and decreased or absent DTR and albumin-cytological dissociation." (PMID 24665332, 2014).
metastasis (10 papers, 2015 to 2025). The spread or migration of cancer cells from one part of the body (where they first appeared) to another. "A correlation between an increase in serum CRP level or a decrease in serum albumin levels with the presence of peritoneal metastasis has been discovered." (PMID 32968368, 2020). "In the present study, the serum albumin levels and AGR were significantly associated with distant LN metastasis, which was the strongest independent predictive factor of PFS and OS." (PMID 32967632, 2020). "Similarly, SFRP2, NKX2-3, and ALB were also a part of the machine learning model for the prediction of liver metastasis in colorectal adenocarcinoma." (PMID 37887568, 2023). "High PLR (HR 1.856, P = 0.002) was an independent predictor of a short OS, along with distant LN metastasis (HR 1.929; P < 0.001), low LMR (HR 1.691; P = 0.041), and low level of serum albumin (< 3.5 g/dL) (HR 1.632; P = 0.043)." (PMID 32967632, 2020). "However, median survival time (MST, P = 0.006), age (P = 0.009), extra pleural metastasis (P = 0.040), WBC (P = 0.013), albumin (P = 0.006), CRP (P < 0.001), CYFRA (P = 0.431), ESR (P < 0.001), NLR (P < 0.001), PLR (P < 0.001), and LMR (P = 0.049) had significant differences among the three groups." (PMID 31837116, 2020).
migraine (10 papers, 2021 to 2026). "Serum Albumin, total bilirubin, uric acid levels, and migraine clinical findings were obtained from medical records." (PMID 36601146, 2023). "Notwithstanding, further investigations are required to better elucidate the association between serum levels of ALB and TBIL and migraine." (PMID 35959386, 2022). "In studies that have compared levels of inflammatory markers in migraine patients, serum NLR, MLR, and the CRP-to-albumin ratio were higher in migraine subtypes during an attack, i.e., migraine with aura, and in patients with a family history of migraine." (PMID 36362765, 2022). "In this study, the serum levels of ALB, TBIL, CRE, and UA were significantly lower in the migraine group than in the HC group, indicating an association between oxidative stress and migraine." (PMID 35959386, 2022). "The serum C-reactive protein, neutrophil, neutrophil/lymphocyte, monocyte/lymphocyte, and C-reactive protein /albumin ratios were higher during migraine attack periods (P < 0.05)." (PMID 35004895, 2021). "The results of our study found lower ALB levels in the patients with migraine." (PMID 35959386, 2022). "The multiple stepwise logistic regression revealed that ALB [odds ratio (OR) 0.79, 95% confidence interval (CI) 0.69–0.89, p < 0.001], TBIL (OR 0.61, 95% CI 0.5–0.75, p < 0.001), and UA (OR 0.97, 95% CI 0.96–0.99, p = 0.014) were independently associated with migraine." (PMID 35959386, 2022). "In addition, reduced ALB, TBIL, and UA were independently associated with migraine." (PMID 35959386, 2022). "By the sex subgroup analysis, the serum CRE and ALB levels of female patients were lower than those of male patients, suggesting weaker antioxidant capacity in women, which may provide a new perspective for explaining the higher incidence of migraine in women." (PMID 35959386, 2022). "The serum levels of ALB, total BIL (TBIL), CRE, and UA were significantly lower in the migraine group than in the control group." (PMID 37891890, 2023). "In a different study, serum ALB, TBIL, and UA levels were found to be significantly lower in migraine patients compared to the control group." (PMID 36601146, 2023). "The study aims to investigate the role of serum albumin (ALB) and creatinine (CRE), bilirubin (BIL), and uric acid (UA) as major intravascular antioxidants in migraine." (PMID 35959386, 2022). "There were highly significant differences in the serum levels of ALB, TBIL, and UA between men and women in the migraine and HC groups (p < 0.05), which indicates a sex-specific difference." (PMID 35959386, 2022). "The effects of sex on the serum levels of ALB, TBIL, CRE, and UA between the migraine and HC groups were determined." (PMID 35959386, 2022). "The serum levels of ALB, total BIL (TBIL), CRE, and UA were significantly lower in the migraine group than in the HC group (p < 0.05)." (PMID 35959386, 2022). "The serum levels of UA, TBIL, ALB, and CRE were lower in the patients with migraine, indicating a lower antioxidant status." (PMID 35959386, 2022). "The serum levels of ALB, TBIL, CRE, and UA were significantly lower in the migraine group than in the HC group (p < 0.05)." (PMID 35959386, 2022). "In our study, we investigated the relationship among serum ALB, TBIL, CRE, and UA levels as indicators of oxidative stress to evaluate the antioxidant status of migraine." (PMID 35959386, 2022). "The serum levels of ALB, TBIL, CRE, and UA were measured in patients with migraine of different subtypes." (PMID 35959386, 2022). "The results of this study showed that compared with the HC group, the serum levels of ALB, TBIL, CRE, and UA were significantly lower in the migraine group." (PMID 35959386, 2022). "Serum levels of ALB, TBIL, CRE, and UA in the migraine and HC groups." (PMID 35959386, 2022).
migraine (continued). "Serum ALB, TBIL, CRE, and UA levels were also investigated in the patients with migraine with different clinical features and subtypes, aiming to determine if any of these markers are protective factors in migraine and explain the role of oxidative stress in etiology." (PMID 35959386, 2022). "Serum levels of UA, TBIL, ALB, and CRE were reduced in the patients with migraine." (PMID 35959386, 2022). "Moreover, there was a significant difference in the serum levels of ALB, TBIL, and UA between men and women in the migraine group on the sex subgroup analysis." (PMID 35959386, 2022). "In addition, the serum levels of ALB, TBIL, and UA were significantly lower in the migraine group when compared by sex." (PMID 35959386, 2022). "Serum levels of UA, TBIL, ALB, and CRE in migraine subtypes." (PMID 35959386, 2022). "In addition, ALB, TBIL, and UA were independently related to migraine." (PMID 35959386, 2022).
mucositis (10 papers, 2017 to 2025). Mucositis is inflammation and damage of the mucous membranes lining the mouth and other parts of the gastrointestinal (GI) tract. "The low specificity of BDG is well known from adult patients and can be caused by several confounding factors including mucositis, bacterial infections or treatment with albumin, immunoglobulins or particular antimicrobial drugs." (PMID 33810069, 2021). "The logistic regression analysis showed that ≥ 3 grade radiation-induced mucositis and a decrease in pre-albumin level to > 15% were more likely to weight loss." (PMID 29137377, 2017). "Although mucositis and a transient drop in albumin levels are common during QS course, these effects are typically manageable and temporary." (PMID 40988098, 2025). "When compared to the Control group, the Mucositis group had substantially higher levels of albumin, ALT, AST, ALP, LDH, amylase, lipase, BUN, creatinine, and TP (p < 0.05–0.0001)." (PMID 36290656, 2022). "Treatment with albumin or immunoglobulins and mucositis as possible sources were found in five of eight patients." (PMID 33810069, 2021). "However, topical administration of bovine lactoferrin on ulcerations in chemotherapy-induced mucositis in hamsters resulted in more and larger ulcerations compared to the control group (treated with bovine serum albumin)." (PMID 33420397, 2021). "In this prospective study a graphic analysis of albumin citrulline and CRP was performed and citrulline was suggested as better biomarker for GI complications, specifically mucositis." (PMID 33488571, 2020). "However, there was a significant difference in albumin, AST, ALT, ALP, LDH, BUN, creatinine, amylase, BUN, and creatinine levels between the ALA + Mucositis group and the Mucositis group (p < 0.05–0.001)." (PMID 36290656, 2022).
non-Hodgkin lymphoma (10 papers, 2013 to 2025). Distinct from Hodgkin lymphoma both morphologically and biologically, non-Hodgkin lymphoma (NHL) is characterized by the absence of Reed-Sternberg cells, can occur at any age, and usually presents as a localized or generalized lymphadenopathy associated with fever and weight loss. "Additionally, the non-Hodgkin’s lymphoma group had lower serum albumin (p = 0.006) and higher serum AST (p = 0.031) compared to the Hodgkin’s lymphoma group." (PMID 35454063, 2022). "To further investigate the relationship between changes in albumin (Alb) levels and the efficacy of targeted therapy in patients with AIDS-related non-Hodgkin lymphoma (AR-NHL), both before and after treatment, we innovatively introduced the Alb Change Rate as a novel indicator." (PMID 41496912, 2025). "The C-reactive protein-to-albumin ratio (CAR) has not been assessed in diffuse large B cell lymphoma (DLBCL, the most common non-Hodgkin lymphoma)." (PMID 33514832, 2021).